SLC35A4 (solute carrier family 35 member A4)
Description:
Required to maintain cellular respiration. Mediates the transport of CDP-ribitol. Does not exhibit CMP-sialic acid, UDP-galactose and UDP-N-acetylglucosamine transport activity.
Tractability: Antibody: UniProt predicts a signal peptide or a membrane-spanning region. PROTAC: its protein half-life has been measured.
Gene: Protein-coding gene on chromosome 5 (140,564,819 to 140,569,100, forward strand). Ensembl gene ENSG00000176087.
Subcellular location: Golgi apparatus membrane; Mitochondrion inner membrane
Subcellular location (Human Protein Atlas): Centrosome; Endoplasmic reticulum
Pathways (Reactome):
Metabolism of proteins: Matriglycan biosynthesis on DAG1
Gene Ontology:
Molecular function: protein binding; pyrimidine nucleotide transmembrane transporter activity; pyrimidine nucleotide-sugar transmembrane transporter activity
Biological process: protein O-linked glycosylation; nucleobase-containing compound transport; organophosphate ester transport; pyrimidine nucleotide transport; pyrimidine nucleotide-sugar transmembrane transport
Cellular component: Golgi membrane; Golgi apparatus; membrane
Genetic constraint (gnomAD): Loss-of-function variants: 9 observed, 19.79 expected, observed/expected ratio (o/e) 0.45, 90% interval 0.27 to 0.79. The upper end of that interval is the gene's LOEUF score, 0.79, which puts it in group 3 of 6, group 1 being the genes least tolerant of losing a copy. Missense variants: 404 observed, 437.61 expected, observed/expected ratio (o/e) 0.92, 90% interval 0.85 to 1. Synonymous variants: 189 observed, 202.67 expected, observed/expected ratio (o/e) 0.93, 90% interval 0.83 to 1.05.
Homologues: Orthologues: macaque SLC35A4 (97% identical), dog SLC35A4 (94% identical), rabbit SLC35A4 (92% identical), rat Slc35a4 (90% identical), guinea pig SLC35A4 (90% identical), pig SLC35A4 (89% identical), mouse Slc35a4 (89% identical), tropical clawed frog slc35a4 (50% identical), Drosophila melanogaster senju (21% identical). Paralogues in human: SLC35A2 (27% identical), SLC35A3 (25% identical), SLC35A1 (23% identical), SLC35A5 (21% identical).
Diseases named in the same sentence as SLC35A4 in open-access papers:
SLC35A4 is named in the same sentence as 10 diseases in open-access papers, as found by Europe PMC text mining. Sharing a sentence is not in itself a finding about the gene and the disease. The quoted sentences say what the papers report.
Alzheimer disease (1 paper, 2024). A progressive, neurodegenerative disease characterized by loss of function and death of nerve cells in several areas of the brain leading to loss of cognitive function such as memory and language. "SLC35A4 is related to epileptic encephalopathy, while H19, ADORA2A and INPP5D are linked to cognitive impairment and Alzheimer's disease." (PMID 39020437, 2024).
colorectal cancer (1 paper, 2025). A primary or metastatic malignant neoplasm that affects the colon or rectum. "Both SLC35A4 and SLC35A5 consistently exhibited lower expression in tumor tissues across all tissue types, including colorectal cancer." (PMID 40303483, 2025). "In our study, we observed that the expression of SLC35A4 and SLC35A5 is decreased in colorectal cancer compared to adjacent non-cancerous tissues." (PMID 40303483, 2025).
Parkinson disease (1 paper, 2020). A progressive degenerative disorder of the central nervous system characterized by loss of dopamine producing neurons in the substantia nigra and the presence of Lewy bodies in the substantia nigra and locus coeruleus. "The loci within these eQTL scores have been reported to regulate expression of genes involved in various brain-related processes and disorders, such as neurite outgrowth and Parkinson’s disease (DCAKD, SLC35A4, SEC14L4, SRA1, NMT1, CPNE1, PLEKHM1, UBE3C)." (PMID 32066731, 2020).
tumor (3 papers, 2009 to 2025). "Overexpressed levels of the SLC35A2 and SLC35A4 proteins was discovered in tumor tissues in a way similarly to patterns reported in BRCA patient samples of the HPA dataset." (PMID 34944621, 2021). "In contrast, the other family members, including SLC35A1, SLC35A3, SLC35A4, and SLC35A5, demonstrated lower expression in tumor tissues." (PMID 40303483, 2025).
SLC35A4 also shares sentences with these, for which no sentence is quoted: autism (1 paper); Cognitive impairment (1); depression (1); Epileptic encephalopathy (1); glioblastoma (1); schizophrenia (1).